PDGFRA (platelet derived growth factor receptor alpha)
Diseases named in the same sentence as PDGFRA in open-access papers (continued):
Sharing a sentence is not in itself a finding about the gene and the disease.
Corneal astigmatism (6 papers, 2011 to 2023). "Here, we performed a comprehensive association analysis of SNPs in the PDGFRA gene region among Japanese patients with corneal astigmatism." (PMID 37752244, 2023). "We performed a comprehensive association analysis of SNPs in the PDGFRA gene region among Japanese patients with corneal astigmatism." (PMID 37752244, 2023). "We found that SNPs in the upstream region of PDGFRA were associated with higher corneal astigmatism in our Japanese population, with ORs increasing with increasing degree of corneal astigmatism." (PMID 37752244, 2023). "In conclusion, to our knowledge, this study is the first to investigate the association between the PDGFRA gene region and corneal astigmatism in individuals of Japanese ancestry." (PMID 37752244, 2023). "To date, the association between the PDGFRA gene region and corneal astigmatism has been assessed in individuals of Chinese, Malay, and Indian ancestry among Asians, but not yet in individuals of Japanese ancestry." (PMID 37752244, 2023). "At the only previously identified genome-wide significant locus for corneal astigmatism, the promoter region of the PDGFRA gene at 4q12, the marker demonstrating strongest association was rs4864857 (P = 1.20 × 10−6)." (PMID 30306274, 2018). "This is especially surprising for the corneal astigmatism-associated SNP at the PDGFRA locus, since this has already been replicated in a cohort of differing ethnicity." (PMID 25367360, 2015). "The purpose of our present study was to investigate the role of the variants near PDGFRA on corneal astigmatism in people of Northern European ancestry." (PMID 23761726, 2013). "Recently, the rs7677751 single nucleotide polymorphism (SNP) at the platelet-derived growth factor receptor alpha (PDGFRA) locus was found to be associated with corneal astigmatism in people of Asian ancestry." (PMID 23761726, 2013). "Variants at the PDGFRA locus have also shown genome-wide significant association with corneal astigmatism." (PMID 23401653, 2013). "In summary, we found no strong evidence for replication or transferability of the previously reported association between the rs7677751 variant, at the PDGFRA locus, and corneal astigmatism in our Australian cohorts of Northern European ancestry." (PMID 23761726, 2013). "Recently, through meta-analysis of five Singaporean cohorts, Fan and colleagues reported a statistically significant association between a variant (rs7677751) at the PDGFRA locus on chromosome 4q12 and corneal astigmatism." (PMID 23761726, 2013). "Our genome-wide meta-analysis across 8,513 individuals in five genome-wide surveys from three genetically diverse populations in Asia reveals that genetic variants in the PDGFRA gene on chromosome 4q12 is significantly associated with corneal astigmatism." (PMID 22144915, 2011). "This highlights the potential role of variants in PDGFRA in the genetic etiology of corneal astigmatism across diverse Asian populations." (PMID 22144915, 2011). "This study aimed to investigate whether SNPs in the PDGFRA region are associated with the risk of corneal astigmatism in a Japanese population." (PMID 37752244, 2023). "In this study, we investigated whether these PDGFRA polymorphisms are associated with corneal astigmatism in a Japanese population." (PMID 37752244, 2023). "The aim of this study was to assess whether polymorphisms in the PDGFRA gene region affected the development of corneal astigmatism in our Japanese population." (PMID 37752244, 2023). "As in Asians, variants at the PDGFRA locus influence corneal curvature (and corneal astigmatism)." (PMID 23401653, 2013). "We observed a strong and consistent association with the onset of corneal astigmatism at the PDGFRA gene locus on chromosome 4q12 across all five Asian cohorts, with three SNPs in this locus exhibiting evidence stronger than genome-wide significance in the meta-analysis." (PMID 22144915, 2011).
Corneal astigmatism (continued). "Variants in PDGFRA on chromosome 4q12 (lead SNP: rs7677751, allelic odds ratio = 1.26 (95% CI: 1.16–1.36), Pmeta = 7.87×10−9) were identified to be significantly associated with corneal astigmatism, exhibiting consistent effect sizes across all five cohorts." (PMID 22144915, 2011). "Our findings suggest the possibility that these PDGFRA SNPs are potential genetic factors in the development of greater corneal astigmatism." (PMID 37752244, 2023). "Genome-wide association studies (GWAS) for refractive astigmatism and corneal astigmatism have identified a single locus for each; in the promoter of PDGFRA (4q12) for corneal astigmatism and near NRXN1 (2p16.3) for refractive astigmatism." (PMID 30306274, 2018). "In light of this, a role for PDGFRA in the regulation of ocular development and parameters cannot be excluded, and our study suggests that genetic polymorphisms within PDGFRA may be involved in the regulation of corneal biometrics resulting in the occurrence of corneal astigmatism." (PMID 22144915, 2011). "Thus, further genetic studies are needed to clarify the contribution of the PDGFRA gene region to the development of corneal astigmatism." (PMID 37752244, 2023). "Our data suggest that the PDGFRA locus does not transfer a major risk of corneal astigmatism in people of Northern European ancestry." (PMID 23761726, 2013). "We did not observe any striking association between the identified variants with either outcomes, suggesting that the association of PDGFRA with corneal astigmatism is probably not through any shared etiology with myopia." (PMID 22144915, 2011). "Thus, PDGFRA variants appear to exert a risk of corneal astigmatism but not spherical refractive error." (PMID 23401653, 2013).
intimal sarcoma (6 papers, 2005 to 2025). A malignant neoplasm arising from the large blood vessels. "Another study of IS, which was the first to propose PDGFRA as a molecular hallmark for intimal sarcomas, found copy number gains of PDGFRA, EGFR, and MDM2 in 8 patients using FISH and aCGH with consistent activation of PDGFR and EGFR confirmed by western blotting." (PMID 31480474, 2019). "Recent studies also reported that PDGFRα and CD44 were positive in intimal sarcoma." (PMID 30925179, 2019).
myocardial infarction (6 papers, 2016 to 2025). Gross necrosis of the myocardium, as a result of interruption of the blood supply to the area, as in coronary thrombosis. "Our study shows that hTERT can activate pro-regenerative signalling within PDGFRα + cMSCs and enhance cardiac repair after myocardial infarction." (PMID 31332256, 2019). "Here we further characterise PDGFRα/CD90-expressing cardiac MSCs (PDGFRα + cMSCs) and use human telomerase reverse transcriptase (hTERT) over-expression to increase cMSCs ability to repair the heart after induced myocardial infarction." (PMID 31332256, 2019). "For example, responses to myocardial infarction were differentially modulated by antibodies against PDGFRβ (inhibition of vascular maturation) or PDGFRα (decreased collagen deposition)." (PMID 27513343, 2016). "However, after myocardial infarction (MI), Pdpn is upregulated in a heterogeneous cell population such as PDGFRα-, PDGFRβ-, and CD34-positive cells, besides lymphatic endothelial cells." (PMID 36970507, 2023). "Particularly, we found that isolation of PDGFRA expressing cardiac stem/progenitor cells were capable of effective differentiation into cardiomyocytes in vitro, and displayed in vivo functional properties when transplanted in the hearts of a rat model of myocardial infarction." (PMID 28410244, 2017). "A study on myocardial infarction using NG2 as a pericyte marker and PDGFRα as a fibroblast marker suggests that a subset of pericytes transiently expressed fibroblast markers, contributing to a minor fraction of fibroblasts." (PMID 39829679, 2025). "LM221 and ONO1301 combination enhanced recruitment of PDGFRα and CD90 double-positive cells, maturation of vessels, and functional recovery in rat acute myocardial infarction hearts, highlighting a new promising acellular approach for the failed heart." (PMID 34782616, 2021). "In vivo, transplantation of hTERT + PDGFRα + cMSCs in athymic rats significantly increased left ventricular function, reduced scar size, increased angiogenesis and proliferation of both cardiomyocyte and non-myocyte cell fractions four weeks after myocardial infarction." (PMID 31332256, 2019).
neurofibromatosis (6 papers, 2010 to 2025). A hereditary neoplastic syndrome in which tumors grow in the nervous system. "Multiple sporadic GISTs have been described in patients who do not have germline mutations in KIT/PDGFRA or neurofibromatosis." (PMID 20946677, 2010). "Conversely, for KIT/PDGFRA WT cases with clinical features of a genetic disease, the multigene second-level panel could help to characterize the NF1-related GIST and to make a diagnosis of neurofibromatosis genetic disease." (PMID 41407759, 2025).
papillary thyroid cancer (6 papers, 2015 to 2022). "Recently platelet derived growth factor receptor-alpha (PDGFRα) was recognized as a potential target to treat aggressive papillary thyroid cancer given its strong association with lymph node metastases." (PMID 27845909, 2016). "We explored the phenotypic changes driven by PDGFRα activation in human papillary thyroid cancer (PTC) cells and the downstream signalling cascades through which they are effected." (PMID 27845909, 2016). "PTX3, COLEC12 and PDGFRA proved to differentiate anaplastic thyroid carcinomas from other subtype while GPR110 seems suitable to become a biomarker for papillary thyroid carcinomas." (PMID 25887408, 2015). "Interestingly enough PDGFRA promotes lymphatic metastases in papillary thyroid cancer." (PMID 25887408, 2015).
acral melanoma (5 papers, 2020 to 2021). "However, it was shown by in vitro analysis that the synonymous polymorphism (c.2472C > T), found in our study, reduces PDGFRα expression in acral melanoma via decreasing its mRNA and protein stability and its downstream signaling activity (MAPK and PI3K/AKT)." (PMID 33213472, 2020). "The driver mutations in the genes RICTOR, CDK4, PDGFRA, KIT were specific for acral melanoma, while the amplification or deletion of the genes CCND2 and CHEK2 are uniquely found in mucosal melanoma." (PMID 32825510, 2020). "The co-amplifications of the receptor tyrosine kinases KIT and PDGFRA on chromosome 4, as well as CDK4 on chromosome 12, are of particular interest for acral melanoma." (PMID 32825510, 2020).
AIDS (5 papers, 2018 to 2022). A syndrome resulting from the acquired deficiency of cellular immunity caused by the human immunodeficiency virus (HIV). "In fact, we were able to identify skin AIDS-KS biopsies in which only a small percentage of phospho-PDGFRA positive KS spindle-cells were LANA positive." (PMID 32603362, 2020). "Among the most promising targeted therapies, Rapamycin, an mTOR inhibitor that targets the KS paracrine oncogenesis axis and the multi-kinase inhibitor Imatinib which targets PDGFRA, c-kit and c-abl showed some responses in transplant and AIDS-KS respectively." (PMID 33057440, 2020). "The clinical relevance of our findings to KS is underscored by the analysis of AIDS-KS tumor biopsies that showed co-distribution of phosphorylated PDGFRA to areas infected with KSHV." (PMID 29985958, 2018). "Analysis of an AIDS-KS TMA showed strong phospho-PDGFRA staining in areas of KSHV-infected LANA+ve spindle cells in ninety percent of the biopsies, indicating that activated PDGFRA is consistently found in most skin AIDS-KS lesions." (PMID 29985958, 2018). "The anti-PDGFRA antibody (Lartruvo/ Olaratumab) acts by blocking the interaction of PDGFs with PDGFRA and has been shown to add a significant benefit to patients receiving only doxorubicin, which in its liposomal form (Doxil) is a frontline therapy to AIDS-KS." (PMID 29985958, 2018). "The existence of a KSHV-induced, ligand-mediated mechanism for PDGFRA activation is supported by immunohistochemistry staining of mECK36 and AIDS-KS lesions showing that the areas staining for both KSHV-LANA and phospho-PDGFRA correspond with the detection of PDGFRA ligands PDGFA and PDGFB." (PMID 29985958, 2018). "The robust activation of PDGFRA signaling observed in mECK36 tumors compared to mECK36 cells in vitro, and in AIDS-KS lesions may be explained by the increased lytic gene expression found in vivo also reported for a portion of KS lesions." (PMID 29985958, 2018). "The results suggest that different CMV-infected cells in the different sites of the GI relating to the expression level of PDGFRα and Nrp2 as well as the vital part of pathological assessment in diagnosing and managing CMV among HIV/AIDS cases." (PMID 35027044, 2022). "To determine the prevalence of PDGFRA activation in AIDS-KS we stained for KSHV LANA and phospho-PDGFRA in skin KS biopsies and controls contained in a tissue microarray developed by the AIDS Cancer Specimen Repository (ACSR)." (PMID 29985958, 2018). "We found that KSHV-LANA staining appears in areas corresponding to phosphorylated PDGFRA, as well as, diffuse PDGFA and PDGFB expression in mECK36 tumors and in AIDS-KS lesions." (PMID 29985958, 2018). "Taken together, our results indicate that prominent PDGFRA phosphorylation occurs in KSHV-infected spindle cells of most AIDS-KS tumors; suggesting that most AIDS-KS patients could be amenable for therapeutic interventions targeting this oncogenic mechanism." (PMID 29985958, 2018).
asthma (5 papers, 2019 to 2025). "This work extends knowledge of the role of PDGFRα+ fibroblasts in allergic airway disease, and loss of fibroblasts before the onset of asthma results in detrimental disease outcomes." (PMID 41146597, 2025). "Furthermore, the loss of PDGFRα+ fibroblasts worsens asthma pathology by creating a lung environment that elevates neutrophil numbers, their activation and mucus production." (PMID 41146597, 2025). "When asthma was induced, we found that loss of PDGFRα+ fibroblasts resulted in increased mucous production, neutrophil activation and proinflammatory cells, such as interstitial macrophages and eosinophils, which can worsen asthma." (PMID 41146597, 2025). "Thus, we sought to determine the effects of fibroblast loss on lung homeostasis and asthma development using a transgenic mouse model to ablate PDGFRα+ fibroblasts." (PMID 41146597, 2025). "Furthermore, our data provide evidence that PDGFRα+ fibroblast loss favors the creation of neutrophilic conditions, accelerating asthma pathology through excessive mucus production, facilitated ECM alteration and increased NETs within the lung." (PMID 41146597, 2025). "Given that PDGFRα+ fibroblasts are necessary for lung repair and remodeling, we utilized a mouse strain in which PDGFRα+ fibroblasts could be eliminated, and we investigated the consequences of their loss on lung homeostasis and asthma pathogenesis." (PMID 41146597, 2025). "Common variants in TGFB1, PDGFRA, and ECM-related genes have been linked to asthma severity, airway wall remodeling, and reduced lung function." (PMID 41279414, 2025). "These mice are therefore suitable for establishing an asthma model to investigate the role of PDGFRα+ fibroblasts in ECM remodeling and disease progression." (PMID 41146597, 2025). "Imatinib, a PDGFRα antagonist, treats asthma by decreasing mast cell activation in patients; imatinib also decreases MCP1 expression in mice." (PMID 37179569, 2023). "To better understand the biological effects of PDGFRα+ fibroblast ablation in the HDM-induced asthma model, we performed microarray analysis to characterize the transcriptomic alterations in chronic asthma, which can provide insight into identifying genes/pathways related to inflammation." (PMID 41146597, 2025). "Variants near or within PDGFRA, such as rs1800810, have been linked to severe nonallergic asthma and enhanced airway remodeling." (PMID 41279414, 2025). "In the context of asthma, the specific involvement and contributions of PDGFRα+ fibroblasts have not been thoroughly explored." (PMID 41146597, 2025).
cervical carcinoma (5 papers, 2006 to 2024). A carcinoma arising from either the exocervical squamous epithelium or the endocervical glandular epithelium. "Sequence analysis of PDGFRα exons 12 and 18 from eight primary cervical cancer cell lines." (PMID 17014709, 2006). "In cervical cancer cells, RTKs, including EGFR and PDGFRα, were significantly downregulated and Akt-mTOR activation was largely inhibited after TN treatment." (PMID 39282148, 2022). "Therefore, TN indeed induced degradation of EGFR and PDGFRα and suppressed PI3K/Akt/mTOR cascade in cervical cancer cells." (PMID 39282148, 2022). "Sequence analysis of PDGFRA exons 12 and 18 from primary cervical cancer tumors and normal cervix samples." (PMID 17014709, 2006).
Duchenne muscular dystrophy (5 papers, 2012 to 2022). Duchenne muscular dystrophy (DMD) is a neuromuscular disease characterized by rapidly progressive muscle weakness and wasting due to degeneration of skeletal, smooth and cardiac muscle. "Duchenne muscular dystrophy (DMD) patients and mdx-mouse models show increased expression of platelet-derived growth factor receptor alpha (PDGFRα), which is an FAP marker." (PMID 35563815, 2022). "PDGF-enriched microenvironment would also contribute to tissue fibrosis as seen in Duchenne muscular dystrophy (DMD), where PDGFRα + Sca1 + CD45− mesenchymal progenitor cells would be activated into tissue remodeling cells after receiving PDGF-AA ligands from the surrounding muscle cells." (PMID 34335301, 2021).
endometrial cancer (5 papers, 2014 to 2025). Primary or metastatic malignant neoplasm involving the endometrium (mucous membrane that lines the endometrial cavity). "PDGFRA was expressed in endometrial carcinoma cells, and regulated endometrial carcinoma cell migration and EMT." (PMID 40661182, 2025). "ABL1 is targeted by Imatinib Mesylate inhibitor which, in a phase I clinical trial for endometrial cancer, while PDGFRA is targeted by Nintedanib, and Dovitinib inhibitors which are currently under phase II clinical trial and Vatalanib as well as Cediranib, inhibitors under phase I clinical trial." (PMID 36704357, 2022). "It has also been recently reported that in vivo models of endometrial cancer exposed to other endocrine-disrupting chemicals such as diethylstilbestrol (DES) aberrantly activated the WNT/β-catenin and TGFβ/PDGFRα-related PI3K/AKT signaling pathways." (PMID 38674005, 2024). "The upregulated hsa-mir-200a-b is associated with the decreased expression of the PTCH1, CCND2, PDGFRA, FOSB and ABL1 genes in endometrial cancer tissue while hsa-mir-429 is correlated with the decreased expression of the ALDH1A1 gene, besides some antibodies, PROTACs and inhibitory molecules." (PMID 36704357, 2022).
eosinophilic disorders (5 papers, 2013 to 2025). "Cytogenetic testing was negative for PDGFRA, PDGFRB, and FGFR1 mutations, ruling out clonal eosinophilic disorders." (PMID 40823575, 2025). "Unlike clonal eosinophilic disorders secondary to PDGFRA and PDGFRB translocations, the WHO-defined CEL-NOS entity is not responsive to imatinib mesylate monotherapy." (PMID 24224106, 2013).